ITPRIP (inositol 1,4,5-trisphosphate receptor interacting protein)
Description:
Enhances Ca(2+)-mediated inhibition of inositol 1,4,5-triphosphate receptor (ITPR) Ca(2+) release.
Synonyms: DANGER; KIAA1754; bA127L20.2; D1A; bA127L20
Tractability: Antibody: UniProt places it where antibodies can reach, with high confidence; UniProt predicts a signal peptide or a membrane-spanning region; its Gene Ontology location is reachable by antibodies, with medium confidence. PROTAC: ubiquitination databases record sites on it; its protein half-life has been measured.
Gene: Protein-coding gene on chromosome 10 (104,309,698 to 104,338,812, reverse strand). Ensembl gene ENSG00000148841.
Subcellular location: Cell membrane; Nucleus outer membrane
Subcellular location (Human Protein Atlas): Vesicles
Gene Ontology:
Molecular function: protein binding; protein kinase inhibitor activity
Cellular component: membrane; nuclear outer membrane; plasma membrane
Genetic constraint (gnomAD): Loss-of-function variants: 32 observed, 37.71 expected, observed/expected ratio (o/e) 0.85, 90% interval 0.64 to 1.14. The upper end of that interval is the gene's LOEUF score, 1.14, which puts it in group 5 of 6, group 1 being the genes least tolerant of losing a copy. Missense variants: 653 observed, 766.62 expected, observed/expected ratio (o/e) 0.85, 90% interval 0.8 to 0.91. Synonymous variants: 358 observed, 337.55 expected, observed/expected ratio (o/e) 1.06, 90% interval 0.97 to 1.16.
Homologues: Orthologues: chimpanzee ITPRIP (99% identical), macaque ITPRIP (98% identical), pig ITPRIP (88% identical), guinea pig ITPRIP (84% identical), rat Itprip (81% identical), rabbit ITPRIP (80% identical), mouse Itprip (78% identical), tropical clawed frog itprip (56% identical), zebrafish itprip (45% identical), zebrafish ITPRIP (33% identical). Paralogues in human: ITPRIPL1 (29% identical), ITPRIPL2 (19% identical), CGAS (14% identical), MAB21L4 (13% identical), MB21D2 (11% identical), TMEM102 (11% identical), MAB21L1 (10% identical), MAB21L2 (10% identical), MAB21L3 (10% identical).
Diseases named in the same sentence as ITPRIP in open-access papers:
ITPRIP is named in the same sentence as 14 diseases in open-access papers, as found by Europe PMC text mining. Sharing a sentence is not in itself a finding about the gene and the disease. The quoted sentences say what the papers report.
Alzheimer disease (2 papers, 2015 to 2017). A progressive, neurodegenerative disease characterized by loss of function and death of nerve cells in several areas of the brain leading to loss of cognitive function such as memory and language. "We discovered age-dependent genetic effects, established associations between vascular-related genes (KLKB1, F12, PLIN2) and midlife plasma aβ levels, and identified a plausible Alzheimer’s Disease candidate gene (ITPRIP) influencing cell death." (PMID 28704393, 2017).
glioma (2 papers, 2020 to 2024). A benign or malignant brain and spinal cord tumor that arises from glial cells (astrocytes, oligodendrocytes, ependymal cells). "The other well-predicted genes, including COL5A1, CPA4, CSTB, and PPIC in gliomas and DAK, ITPRIP, TM4SF19, TMEM200A in RCC have not been studied thoroughly in cancer and their roles in cancer worth further investigating." (PMID 32194984, 2020).
lung carcinoma (2 papers, 2016 to 2024). "Similarly, the genes PAPSS2 and ITPRIP have been recognized as unfavourable prognostic factors across a spectrum of cancers, including thyroid, colorectal and lung cancers." (PMID 38894657, 2024).
Stroke (2 papers, 2017). Sudden impairment of blood flow to a part of the brain due to occlusion or rupture of an artery to the brain. "Reduction of IP3R–mediated calcium signaling rescued presenilin-associated AD pathogenesis in mouse models, thus drugs that enhance ITPRIP activity may prevent cell death in neurodegenerative diseases and stroke." (PMID 28704393, 2017).
colon cancer (1 paper, 2022). "ITPRIP has also been reported in patients with colon cancer." (PMID 36189217, 2022).
cancer (6 papers, 2016 to 2025). A tumor composed of atypical neoplastic, often pleomorphic cells that invade other tissues. "Less information are available for six of the genes in the panel in relation to cancer namely the ITPRIP, FRMD6, CPXCR1, SLC38A9, MRPL52 and GFRA4." (PMID 27609023, 2016).
tumor (2 papers, 2016 to 2024). "Furthermore, a survival analysis was conducted on the individual genes comprising the UBE2C+ tumour cell score, and it revealed statistically significant results for ITPRIP, GJA1, RUNX1T1, CD82, PAPSS2 and ANXA5." (PMID 38894657, 2024).
ITPRIP also shares sentences with these, for which no sentence is quoted: colorectal cancer (1 paper); early-onset Alzheimers disease (1); epilepsy (1); ischemia (1); neurodegenerative disease (1); neurological disorders (1); non-small cell lung carcinoma (1).